COL5A1 (collagen type V alpha 1 chain)
Diseases named in the same sentence as COL5A1 in open-access papers (continued):
Sharing a sentence is not in itself a finding about the gene and the disease.
Autoimmunity (1 paper, 2020). The occurrence of an immune reaction against the organism's own cells or tissues. "Although further research is needed to assess the importance of the α2(V) chain in the pathogenesis of SSc, the dataset of this study suggests a potential role for the α1(V) chain and its Col5A1(1049) and Col5A1(1439) peptides in autoimmunity in SSc." (PMID 33643291, 2020). "In agreement with the immunofluorescence results that showed autoimmunity to the α1(V) chain in SSc, we also detected a significant expression of autoantibodies to the Col5A1(1049) and Col5A1(1439) peptides of the α1(V) chain." (PMID 33643291, 2020). "We found that the reactivity between sera from early-SSc patients anti-Col V positive and SSc-ILD lung biopsies related strongly to autoimmunity to α1(V) chain, specially involving two immunogenic α1(V) chain peptides (Col5A1(1049) and Col5A1 (1439))." (PMID 33643291, 2020).
benign glioma (1 paper, 2022). "Furthermore, high levels of HK2 are correlated with high levels of COL5A1 in patients with GBM relative to benign glioma." (PMID 35158782, 2022). "High levels of NOX2 are correlated with high levels of COL5A1 and the accumulation of extracellular matrix (ECM) in patients with GBM relative to benign glioma." (PMID 35158782, 2022).
Birt-Hogg-Dube syndrome (1 paper, 2023). "We present a case of a 22-year-old male with Birt-Hogg-Dubé syndrome, showing typical features consistent with the classical type of EDS, with genetic testing revealing a COL5A1 mutation of "uncertain clinical significance", not yet reported in clinical literature." (PMID 36895521, 2023).
brain cancer (1 paper, 2024). A primary or metastatic malignant neoplasm affecting the brain. "Notably, genes linked to brain cancer progression and tumor immunity (ENO1, MUC1, COL5A1, and IL11) were significantly downregulated (>2-fold) in KO brain tissue but were upregulated in FABP7 OV astrocytes." (PMID 39596296, 2024). "We also found that the expression of the onco-immune factors (ENO1, MUC1, COL5A1, IL11) that we identified was significantly correlated with FABP7 expression in patient brain cancers, particularly LGG, suggesting the pathological relevance of the results of our transcriptomic analyses." (PMID 39596296, 2024).
brain tumor (1 paper, 2021). "We also determined the protein level of COL5A1 and examined its use as a prognostic factor for tumor staging in brain tumor patients." (PMID 34702798, 2021).
cataract (1 paper, 2022). Partial or complete opacity of the crystalline lens of one or both eyes that decreases visual acuity and eventually results in blindness. "For example, COL5A1 and NHS, both genes bearing endogenous CTG/CAG repeats, therefore potential silencing targets of the toxic siRNAs, are known causes of cataract." (PMID 36060259, 2022).
central centrifugal cicatricial alopecia (1 paper, 2025). "Similarly, COL5A1, involved in collagen fibril organization, was upregulated in central centrifugal cicatricial alopecia (CCCA)." (PMID 40475059, 2025).
cervical squamous cell carcinoma (1 paper, 2022). A squamous cell carcinoma arising from the cervical epithelium. "Meanwhile, lower COL5A1 expression was detected in 3 cancers compared to normal tissues, including cervical squamous cell carcinoma (CESC), uterine corpus endometrial carcinoma (UCEC), and kidney renal papillary cell carcinoma (KIRP)." (PMID 35082969, 2022).
Classical Ehlers-Danlos syndrome (1 paper, 2019). "Classical Ehlers-Danlos syndrome (cEDS) is a dominant inherited connective tissue disorder mainly caused by mutations in the COL5A1 and COL5A2 genes encoding type V collagen (COLLV), which is a fibrillar COLL widely distributed in a variety of connective tissues." (PMID 30716086, 2019).
dislocation (1 paper, 2023). A displacement of a part (especially a bone) from its normal position. "The aim of this study was to assess the coexistence of polymorphisms of the COL1A1 and COL5A1 genes with clinically diagnosed laxity and the occurrence of recurrent patellar dislocation in adolescents." (PMID 38102224, 2023). "Therefore, the aim of this study was to assess the coexistence of polymorphisms of the COL1A1 and COL5A1 genes with clinically diagnosed laxity and the occurrence of recurrent patellar dislocation in adolescents." (PMID 38102224, 2023).
emphysema (1 paper, 2022). "Given the emphysema‐like changes observed in Col5a1+/− mice histological sections and from histomorphometric measurements, decreased Rn and tissue elasticity (H) may be expected, as demonstrated in other mouse models of emphysema." (PMID 35439366, 2022). "We used mice that are haploinsufficient for Col5a1 (Col5a1+/−), a well‐accepted model of classical EDS type, and demonstrated the presence of primary changes in the lung parenchyma that are reminiscent of emphysema." (PMID 35439366, 2022).
epilepsy (1 paper, 2022). A brain disorder characterized by episodes of abnormally increased neuronal discharge resulting in transient episodes of sensory or motor neurological dysfunction, or psychic dysfunction. "Epilepsy has been noted in human patients with EDS and is associated with many structural brain defects, including periventricular heterotopia in patients with COL5A1 variants." (PMID 35627182, 2022).
Epiphyseal dysplasia (1 paper, 2026). "The COL5A1 gene is contained in equine chromosome (ECA) 25, around the QTL for OCD of the fetlock, and is associated with epiphyseal dysplasia." (PMID 40302410, 2026). "The collagen type 27 alpha 1 (COL27A1) gene, as COL5A1, is contained in equine chromosome 25, around the QTL for OCD on the fetlock, and is also associated with epiphyseal dysplasia." (PMID 40302410, 2026).
glomerulosclerosis (1 paper, 2021). A hardening of the kidney glomerulus caused by scarring of the blood vessels. "As molecular drivers of glomerulosclerosis in diabetic UNx and UNx-Renin mice, our glomerular gene expression analysis confirmed the upregulation of several fibrogenesis-associated genes (e.g. Col1a1, Col5a1, Col5a3, Fn1 and Mmp14)." (PMID 34494644, 2021).
hearing loss (1 paper, 2023). "We also identify four additional novel candidate genes (COL5A1, HMMR, RAPGEF3, and NNT) in which rare variant burden may be associated with hearing loss." (PMID 36656851, 2023).
heart hypertrophy (1 paper, 2013). "We have provided evidence that AA development in mice is associated with abnormal heart hypertrophy, associated with elevation of Il18, Col5a1 and cardiac remodelling marker, cTnI." (PMID 23658656, 2013).
Hyperglycemia (1 paper, 2021). An increased concentration of glucose in the blood. "Further studies are needed to better understand the effects of hyperglycemia and increased AGE-mediated crosslinking on the various collagen isoforms in DM corneas, and to determine whether sequence variants in or near COL5A1 are associated with KC and DM cornea pathology." (PMID 34746916, 2021).
injury (1 paper, 2024). Damage inflicted on the body as the direct or indirect result of an external force, with or without disruption of structural continuity. "COL5A1, encoding type V collagen, although it does not account for a large proportion of fibrous scars formed after heart injury, plays an important role in regulating the size of fibrous scars." (PMID 38921668, 2024).
Insulin resistance (1 paper, 2021). Increased resistance towards insulin, that is, diminished effectiveness of insulin in reducing blood glucose levels. "Another study showed higher DNA methylation of COL5A1 in the VAT of women with insulin resistance, revealing an epigenetic regulation of COL5A1 and its implication in pathways related to integrin cell interactions and insulin signaling in VAT." (PMID 33803198, 2021).
intracranial aneurysm (1 paper, 2020). "The most noteworthy vascular complaints in our cohort were two aortic ectasias, an arteriovenous fistula, an interatrial septal aneurysm and an intracranial aneurysm; all these issues, except one of the two z scores > 2, were recognized in adults harboring a COL5A1 null allele." (PMID 32736638, 2020).
leukemia (1 paper, 2022). A malignant (clonal) hematologic disorder, involving hematopoietic stem cells and characterized by the presence of primitive or atypical myeloid or lymphoid cells in the bone marrow and the blood. "We found that COL5A1 was highly expressed in most human cancers, including the brain and central nervous system (CNS), breast, colorectal, esophageal, gastric, head and neck, kidney, leukemia, liver, lung, lymphoma, ovarian, pancreatic, sarcoma, and other cancers." (PMID 35082969, 2022).
multifocal fibromuscular dysplasia (1 paper, 2025). "Heterozygous variants in COL5A1 are associated with Ehlers–Danlos syndrome, classic type 1 (OMIM 130000), and multifocal fibromuscular dysplasia (OMIM 619329)." (PMID 40282419, 2025).
multiple sclerosis (1 paper, 2015). A progressive autoimmune disorder affecting the central nervous system resulting in demyelination. "COL1A1, COL3A1, COL5A1, and COL5A2 chains were induced significantly in active multiple sclerosis lesions and even more in inactive lesions." (PMID 26691002, 2015).
ovarian tumours (1 paper, 2020). "Also, in primary ovarian tumours, the highly expressed COL5A1 was found to be associated with poor prognosis and high risk of metastasis." (PMID 32720739, 2020).
Pectus excavatum (1 paper, 2025). A defect of the chest wall characterized by a depression of the sternum, giving the chest ("pectus") a caved-in ("excavatum") appearance. "Recently, the presentation of a patient with KC and pectus excavatum was reported with mutations in COL5A1, further hypothesizing the role of COL5A1 in altering collagen pathways in the cornea." (PMID 41153364, 2025).
periodontitis (1 paper, 2025). An acute or chronic inflammatory process that affects the tissues that surround and support the teeth. "Moreover, there are a few dental clinics in the United States that offer genetic testing for aggressive periodontitis (AP) and Sjogren’s syndrome by testing mutations in Cathepsin C (CTSC), LYST, COL5A1, FcyIIB, and FPRI for AP." (PMID 40136761, 2025).
skin aging (1 paper, 2015). The gradual irreversible changes in structure of skin that occur as a result of the passage of time.. "Indeed, we detected a set of metallo-proteinases (MMP2, MMP14), collagens (e.g. COL6A1, COL3A1, COL5A1 and others) and elastin (ELN), which showed a significant longitudinal change in expression in addition to being closely correlated to skin aging." (PMID 25977295, 2015).
stomach adenocarcinoma (1 paper, 2022). "After that, we investigated whether the high expression of dual combinations of COL1A1, COL1A2, COL3A1, or COL5A1 exacerbates the outcome of CAF infiltration in stomach adenocarcinoma." (PMID 35739492, 2022). "With further analysis, we revealed COL1A1, COL5A1, ITGA4, EMILIN1, and TSPAN9 as a poor prognostic gene signature for CAF infiltration, with high specificity to stomach adenocarcinoma." (PMID 35739492, 2022). "We also investigated the impact of CAF markers highly clustered with COL1A1 and COL5A1 in correlation analysis, namely THBS2, FAP, INHBA, S100A4, COL11A1, or MMP11, on the outcome of CAF infiltration in stomach adenocarcinoma." (PMID 35739492, 2022). "Despite that, adding TSPAN9 to the COL1A1, COL5A1, ITGA4, and EMILIN1 Cox model further increased the hazard ratio to 36.813 for CAF infiltration in stomach adenocarcinoma samples." (PMID 35739492, 2022). "All this data suggested COL1A1, COL5A1, ITGA4, EMILIN1, and TSPAN9 as a poor prognostic CAF signature with high specificity to stomach adenocarcinoma." (PMID 35739492, 2022). "Based on the comparative pan-cancer analysis of these key CAF markers and a comprehensive literature search we identified COL1A1, COL5A1, ITGA4, EMILIN1, and TSPAN9 as the signature genes, which potentiated the poor prognostic impact of CAF infiltration specifically in stomach adenocarcinoma." (PMID 35739492, 2022). "However, the addition of FN1 to the COL1A1, COL5A1, and ITG4 Cox regression model decreased the poor prognostic impact of CAF in stomach adenocarcinoma." (PMID 35739492, 2022).
thrombosis (1 paper, 2025). "In the current study, COL5A1, VCAN, PTGS2, ITGAV and ITGA8 were five hub genes revealed to be closed associated with thrombosis-prone plaques." (PMID 41415585, 2025). "Among them, COL5A1, VCAN, PTGS2, and ITGAV showed extremely significant increases (P < 0.01); ITGA8 was significantly decreased in the plaque group and thrombosis group (P < 0.01)." (PMID 41415585, 2025).
type 2 diabetes (1 paper, 2023). "On the contrary, the SAT expression of COL5A1 and COL6A3 was associated with %TBWL after BS (both p < 0.001), even after adjusting for age, gender, baseline BMI, and type 2 diabetes status (T2D)." (PMID 37174662, 2023).
vascular EDS (1 paper, 2020). "Embryos lacking functional col5a1 genes develop spontaneous hemorrhages in the trunk under normal physiological conditions, reminiscent of easy bruising in patients with vascular EDS." (PMID 33104690, 2020).
tumor (84 papers, 2012 to 2026). "Ligand-receptor pairs linked to high-risk tumors, including IL1A_IL1RAP, COL5A1_ITGB1, APP_NCSTN, PLAU_ITGA5, AGRN_ITGB1, and LAMC2_ITGA6, were found to be particularly enriched in tumor regions." (PMID 40021759, 2025). "The hub gene COL5A1 is supposed to be significantly associated with tumor infiltrating immune cells and can be potential targets for prognosis in GC." (PMID 40386054, 2025). "Then, the prognostic value, co-expressed gene cluster and involved pathways, biological processes, and associated tumor-infiltrating immune cells in respect of COL5A1 were explored via bioinformatic analysis." (PMID 34868960, 2021). "COL1A2, COL3A1, COL5A1 encode the collagen family, whose members are the main components of the tumor-stromal environment and play an important role in behavior of cancer cells." (PMID 34795689, 2021). "The present study examined the biological functions, prognostic value, and gene-associated tumor-infiltrating immune cells of COL5A1 through experiments and bioinformatics analysis." (PMID 34868960, 2021). "Real‐time PCR and Western Blot analysis were used to study the differentiated expression of miR‐145, MALAT1 (metastasis‐associated lung adenocarcinoma transcript 1) and COL5A1 (collagen alpha‐1(V) chain) in tumour/serum samples genotyped as rs619586 AA, AG and GG." (PMID 32720739, 2020). "Therefore, all three of these genes could be potentially good candidates for further study, especially GOLPH3 and COL5A1, whose expressions were found to be associated with tumor progression in other tumor types." (PMID 38173042, 2024). "In addition, COL5A1 was reported to be negatively related to tumor purity but positively linked to immune cell infiltration, and the COL5A1-mediated cell proliferation of STAD may be mediated by effects on the TME." (PMID 35082969, 2022). "Among tumor differentiation grade-related genes in the prognostic signature, collagen type V alpha 1 (COL5A1) is a key molecular node." (PMID 40386054, 2025). "In the HPA database, the protein expression of SERPINH1 and COL5A1 was higher in tumor tissues than in normal tissues." (PMID 40530702, 2025). "The levels of genes associated with tumor metastasis, including MAPK1, MAPK14, COL5A1, FN1, EP300, and FOSL2, were significantly downregulated after SH intervention." (PMID 41444284, 2025). "Subcluster 1 exhibited pronounced upregulation of extracellular matrix (ECM)‐related genes (COL6A3, COL5A1) in tumor samples compared to normal tissues." (PMID 41057994, 2025). "While the enrichment of ECM-related pathways is in line with the known roles of THBS2, FN1, COL1A1, and COL5A1 in extracellular matrix remodelling and tumour progression, the concurrent upregulation of mTOR signalling presents an intriguing finding." (PMID 40860666, 2025). "A specific analysis of known cancer driver genes revealed NRAS as the most frequently mutated gene (6/8 tumor populations), followed by KMT2D (5/8 tumor populations) and COL5A1 (5/8 tumor populations)." (PMID 40004220, 2025). "For example, in COL1A1, COL1A2, COL3A1 and COL5A1 HYP peptides were enriched in the tumor nodule boundaries, a pattern that was lost in P4HA2-depleted tumors." (PMID 40671813, 2025). "All four candidate genes (THBS2, FN1, COL1A1, COL5A1) were found to be upregulated in tumour samples compared to matched normal samples in our microarray analysis." (PMID 40860666, 2025). "Scientific literature data prove that the overexpression of COL5A1 promotes tumor progression and metastasis and correlates with poor patient survival." (PMID 39859451, 2025). "Extensive research has revealed that COL5A1 is overexpressed in numerous malignancies, playing a crucial role in fostering tumor progression, conferring resistance to chemotherapy, and regulating the immune microenvironment." (PMID 39551792, 2024).